MIR7113 (microRNA 7113)
Synonyms: hsa-mir-7113
Gene: MicroRNA gene on chromosome 11 (68,032,864 to 68,032,922, forward strand). Ensembl gene ENSG00000284293.
Homologues: Orthologues: chimpanzee MIR7113 (100% identical).